GAS6 (growth arrest specific 6)
Diseases named in the same sentence as GAS6 in open-access papers (continued):
Sharing a sentence is not in itself a finding about the gene and the disease.
kidney diseases (9 papers, 2007 to 2023). "Drawing from other research, the Gas6/AXL pathway has been implicated in the pathogenesis of kidney diseases." (PMID 37813528, 2023). "The results from these studies strongly suggest a beneficial role of Gas6 in kidney disease, at least in the mammal models." (PMID 30934817, 2019). "Second, tubular interstitial injury is a common mediator of CKD progression and finally, that we did not detect any glomerular or sclerotic defects that have previously been shown to be modified by Gas6/Axl signalling in other models of kidney disease." (PMID 25019319, 2014). "Among them, Axl has the highest binding affinity with Gas6 and is expressed in endothelial and mesangial cells in animal kidney disease models." (PMID 23826128, 2013). "Because warfarin therapy is sometimes applied to IgAN patients, the role of Gas6/Dtk in podocytes should be clarified in the further study by finding and analyzing an animal kidney disease model in which Gas6/Dtk pathway is involved." (PMID 23826128, 2013). "Increased glomerular expression of Gas6 has been detected in animal models of kidney disease, and Gas6 knockout mice were shown to be resistant to accelerated nephrotoxic nephritis." (PMID 17241453, 2007). "Therefore, in this study we used the potent and selective AXL inhibitor CH5451098 to elucidate the role of Gas6/AXL in kidney diseases." (PMID 32324796, 2020). "Gas6 is a growth factor which is post-translationally modified with γ- carboxylation of glutamate residues at its N terminus in the presence of vitamin K and inhibited by warfarin, an optional therapy for human kidney diseases." (PMID 23826128, 2013). "However, the expression of Gas6 in human kidney diseases is still unclear and yet to be fully examined." (PMID 23826128, 2013). "Moreover, Axl/Gas6 signalling might be a new therapeutic target for kidney diseases induced by GO-LDL." (PMID 23226259, 2012). "While previous studies using Gas6−/− mice suggest that such inhibitors may be of therapeutic use in some renal pathology this article and previous work on Axl in VC indicate that such inhibitors should be studied in humans with caution, particularly in patients with renal disease." (PMID 25019319, 2014). "Previous data suggest that Gas6 induces mesangial cell proliferation via the latent transcription factor STAT3, which may be a therapeutic target for the treatment of renal disease." (PMID 23226259, 2012).
neurodegenerative disease (7 papers, 2018 to 2025). A disorder of the central nervous system characterized by gradual and progressive loss of neural tissue and neurologic function. "The biological importance of Gas6–Tyro3 ligand/receptor interaction remains incompletely understood, and only a few studies have implicated Gas6–Tyro3 signaling in neurodegenerative diseases." (PMID 29382817, 2018). "In neurodegenerative diseases, characterized by the accumulation of apoptotic cells and debris in the brain, GAS6 enhances the clearance of apoptotic neurons by microglial cells and reduces neuroinflammation." (PMID 38817615, 2024). "Studies have suggested that GAS6 levels may be dysregulated in neurodegenerative diseases such as AD." (PMID 39050669, 2024).
neurologic disorder (5 papers, 2010 to 2024). "The concentration of Gas6 was increased in the patients with a history of neurologic disorder and acute activity in the BILAG hematology system." (PMID 20637106, 2010). "Gas6 levels were elevated in patients with a history of neurologic disorder." (PMID 20637106, 2010). "Furthermore, the measurement of vitamin K-dependent Gas6 functionality could be an indicator of homeostatic or disease mechanisms in the brain, such as in neurological disorders where Gas6/TAM signalling is impaired." (PMID 38786095, 2024). "This highlights the relevance of Gas6-TAM-receptor-related studies in finding vaccines and antivirals for ZIKV-induced neurological disorders." (PMID 36680287, 2023). "Gas6 levels in SLE patients differed little from levels in NC, but they were elevated in the small numbers of patients with a history of neurological disease." (PMID 20637106, 2010). "Although the number of patients with a history of neurologic disorder was only five, they had elevated Gas6 levels compared with patients without a history of neurologic disorder." (PMID 20637106, 2010).
bacterial infection (3 papers, 2018 to 2023). "Prior to bacterial infection, 57-week-old mice received three intraperitoneal injections of Gas6 recombinant protein (125 μg protein/kg) every 24 h." (PMID 37289655, 2023). "One of the target cells of GAS6 in bacterial infection is the vascular endothelium, which showed reduced LPS-induced permeability in the presence of GAS6." (PMID 34344929, 2021). "Taken together, it can be concluded that GAS6 has opposing roles during bacterial infection." (PMID 29967614, 2018).
hematologic disease (3 papers, 2010 to 2020). "Besides, emerging evidence indicate that high expression of Gas6 is associated with a poor prognosis in hematologic malignancies." (PMID 32298237, 2020). "Surprisingly, active hematologic disease as defined by BILAG revealed an unexpected association with elevated, not reduced Gas6 levels." (PMID 20637106, 2010).
inflammation (3 papers, 2022 to 2025). Aberrant reaction of the microcirculation characterized by movement of fluid and leukocytes from the blood into extravascular tissues. "GAS6 is also known to be expressed in chronic inflammatory conditions, and GAS6 deficiency has been shown to prevent liver inflammation and fibrosis, potentially by restoring AXL on KCs." (PMID 37004869, 2023). "Furthermore, the fact that the lung infiltration and pro-inflammatory cytokines are reduced during AXL inhibition confirms a possible direct role for Gas6/AXL signaling in lung inflammation and the development of PE." (PMID 35741013, 2022). "GAS6 also increases endothelial cell activation in response to inflammatory stimuli and accelerates the circulation of platelets and leukocytes in blood, which may be indicative of chronic systemic inflammation." (PMID 40943271, 2025). "This suggested a role for GAS6/AXL signaling and the development of lung inflammation in this model of PE." (PMID 35741013, 2022).
retinopathy (2 papers, 2014 to 2025). "sMer can bind to Gas6 and inhibit Gas6-mediated MERTK activation, which in turn could result in the impaired phagocytosis and retinopathy." (PMID 25517981, 2014).
infectious disease (1 paper, 2023). A disorder directly resulting from the presence and activity of a microbial, viral, or parasitic agent in humans. "From these findings, we conclude that the age-related decrease in Gas6 secretion in the intestinal mucosa is the reason why K. pneumoniae can be pathogenic in the elderly, thereby indicating that Gas6 could be effective in protecting the elderly against infectious diseases caused by gut pathogens." (PMID 37289655, 2023).
psychiatric disorder (1 paper, 2021). A disorder characterized by behavioral and/or psychological abnormalities, often accompanied by physical symptoms. "Thus, based on AXL-induced phagocytic astrocytes that respond to active microglia-derived GAS6 after TBI, we connected the glial function with acute neurological and later psychiatric disorders that could be manipulated in the early stages." (PMID 34233703, 2021).
GAS6 also shares sentences with these, for which no sentence is quoted: thrombosis (4 papers); bone metastasis (2); chronic lymphocytic leukaemia (2); chronic periodontitis (2); Clear Cell Renal Cell Carcinoma (2); esophageal varices (2); metabolic disorders (2); multiple myeloma (2); renal failure (2); small cell lung carcinoma (2); abdominal aortic aneurysm (1); adenocarcinoma (1); allergic asthma (1); amyotrophic lateral sclerosis (1); aortic aneurysm (1); atrial fibrillation (1); autoimmune thyroiditis (1); bladder infection (1); bladder tumours (1); brain cancer (1); brain tumor (1); breast (1); carcinoma in situ (1); Cerebral ischemia (1); cholangiocarcinoma (1); chromophobe renal cell carcinoma (1); coagulopathy (1); dilated cardiomyopathy (1); Dyspareunia (1); Encephalopathy (1).
A further 29 diseases each share a sentence with GAS6 in 1 paper.